TERT-DT (TERT divergent transcript)
Synonyms: hTAPAS
Gene: Long non-coding RNA gene on chromosome 5 (1,295,139 to 1,296,787, forward strand). Ensembl gene ENSG00000300381.
Diseases named in the same sentence as TERT-DT in open-access papers:
TERT-DT is named in the same sentence as 10 diseases in open-access papers, as found by Europe PMC text mining. Sharing a sentence is not in itself a finding about the gene and the disease.
TERT-DT shares sentences with these, for which no sentence is quoted: cancer (5 papers); B-cell lymphomas (1); cervix carcinoma (1); glioblastoma (1); hepatocellular carcinoma (1); liver cancer (1); lymphoma (1); prostate carcinoma (1); tumor (1); urothelial carcinoma (1).